MMP9 (matrix metallopeptidase 9)
Diseases named in the same sentence as MMP9 in open-access papers (continued):
Sharing a sentence is not in itself a finding about the gene and the disease.
Stroke (continued). "The results showed that MMP-9 activity was significantly increased after ischemia and further enhanced by delayed tPA, and these effects were profoundly inhibited by combination treatment of tPA + J147 and J147, with a substantial improvement of collagen-IV degradation after stroke." (PMID 35309561, 2022). "Finally, MMP-9-positive neutrophils have been found surrounding brain microvessels with severe type IV collagen degradation and BBB breakdown in patients with stroke, clearly showing a strong association between neutrophils, MMP-9 and BBB damage also during human CNS disease." (PMID 36034148, 2022). "MMP-9 upregulation correlates remarkably with disruption of the PNN in an overwhelming number of studies on epilepsy, TBI and stroke, glioblastoma, neurodegenerative and neuropsychiatric diseases, and blocking MMP-9 activity generally prevents PNN disruption and improves the disease pathologies." (PMID 36339816, 2022). "Whether catalpol treatment of stroke is related to MMP9 needs further verification." (PMID 33505489, 2021). "After stroke, high levels of MMP9 and Fn1 may represent severe damage to neurovascular units." (PMID 34630032, 2021). "However, MMP-9 activity after stroke was decreased in NSC-transplanted young adult and aged mice." (PMID 34299322, 2021). "In parallel, studies employing MMP-9−/− mice showed that leukocyte-derived MMP-9 plays an essential role in mediating BBB dysfunction and is associated with elevated leukocyte transmigration that exacerbates the inflammatory signaling in the acute phase of stroke." (PMID 34566627, 2021). "Consequently, downregulating leukocyte recruitment and MMP-9 could be a promising strategy to ameliorate BBB leakage after stroke." (PMID 34576209, 2021). "The current knowledge implies that MMP-9 impact on BBB breakdown and neurodegeneration is time and context-dependent, which entails a contextualized modulation of protein expression/activity to preserve BBB integrity and attenuate cognitive deficits associated with stroke." (PMID 34566627, 2021). "Indeed, inhibition of MMP-9 at 24–48 h after stroke worsens outcome in animal models." (PMID 34054705, 2021). "Thus, MMP-9 inhibition is thought to be a potential target for stroke therapy." (PMID 32191628, 2020). "Furthermore, MMP-9 was found to play a role in post-stroke depression." (PMID 32466129, 2020). "Our study demonstrated that the expression and activity of both MMP2 and MMP9 in BM animal model are upregulated by exogenous Poldip2 and downregulated by Poldip2 knockdown, corroborating the results of previous studies in hindlimb ischemia‐induced mice and stroke animal model." (PMID 32790044, 2020). "Furthermore, MMP9 appears to contribute to both neuronal cell loss following TBI and the facilitation of regenerative processes Interestingly, clinical studies have found that MMP9 in cerebrospinal fluid was elevated in stroke and TBI patients." (PMID 32878052, 2020). "Thus, we reason that the variants in MMP‐9 gene could potentially provide these individuals with higher concentration of MMP‐9, result in BBB destruction, apoptosis, and neuronal damage, thereby increasing the risk of END and stroke severity in these patients." (PMID 31012282, 2019). "In subacute and chronic phases of stroke, infiltrating leukocytes release cytokines and chemokines, and excessive production of reactive oxygen species (ROS) leads to induction/activation of matrix metalloproteinases (especially MMP-9) amplifying the inflammatory response in brain." (PMID 30800679, 2019). "In addition to the approaches to address MMP-9 as a target in neoplastic, vascular, and other diseases, it is also regarded as a promising diagnostic or prognostic factor, e.g., in inflammatory bowel disease or stroke, rendering MMP-9 an interesting potential biomarker." (PMID 30935029, 2019).
Stroke (continued). "Also, MMP-9 activity during the delayed neuroinflammatory response may contribute to remodeling and stroke recovery, but MMP-9 activity in the acute stroke stage can exacerbate BBB leakage as well as brain damage." (PMID 30705764, 2019). "Expression of matrix metalloproteinase-9 (MMP-9), an enzyme involved in the degradation of the extracellular matrix, was significantly higher in old stroke subjects (> 71 years old) compared to both age-matched controls and young (≤ 71 years old) stroke subjects." (PMID 29752550, 2018). "However, in this study, stroke severity and cognitive function before standard rehabilitation therapy were associated with MMP-9, not serum mature BDNF." (PMID 30322026, 2018). "Post-stroke STS treatment could improve neurologic functional outcomes for acute ischemic stroke patients following rt-PA treatment by reducing BBB leakage and damage, which might be mechanistically associated with MMP-9 inhibition." (PMID 28243834, 2017). "Furthermore, the MMP-9/TIMP-1 ratio has been proposed as a marker of stroke." (PMID 26973468, 2016). "The present study was designed to determine the molecular effects of rTMS on serum levels of mature BDNF, proBDNF and MMP-9 in poststroke patients with upper limb hemiparesis, and the relationship between serum biomarkers and functional evaluation of upper limb hemiparesis in patients after stroke." (PMID 27007747, 2016). "Interestingly, RWJ67657 significantly inhibited MMP-9 activity on days 7 and 14 post-stroke." (PMID 26581247, 2015). "Along the same lines is the finding of upregulation of MMP-9, which in chronic stroke may be involved in neurovascular remodeling, thus promoting brain tissue repair and regeneration during delayed phases after stroke." (PMID 26431529, 2015). "However, the timing of inhibition is critical and late MMP9 inhibition may be deleterious, suggesting a role for MMP-9 in delayed cortical response and recovery after stroke." (PMID 26074872, 2015). "Moreover, adjudin obviously inhibited the elevated MMP-9 activity after stroke." (PMID 24927761, 2014). "In regard to inflammation, MMP-9 facilitates migration of inflammatory cells by cleaving inflammatory cytokines and chemokines in several inflammatory diseases, such as Alzheimer's disease, Parkinson disease, and multiple sclerosis, or after stroke or spinal cord trauma." (PMID 25186151, 2014). "Because oxidative and nitrosative stress might promote capillary constriction after ischemia, and S-nitrosylation contributes to MMP-9 activation after stroke, it is reasonable to consider pericytes as critical targets for MMP-9 proteolytic activity after cerebral ischemia." (PMID 22587708, 2012). "Thus, MMP-9 can be a potential therapeutic target for the treatment of stroke." (PMID 20514206, 2009). "However, MMP-9 has biphasic roles in stroke pathophysiology." (PMID 20514206, 2009). "But MMP-9 may have a different role during delayed phases after stroke." (PMID 20514206, 2009). "As continuous variables, IL-6 (p = 0.02), CRP (p = 0.03), MMP-9 (p = 0.004), D-dimer (p < 0.001), LDL (p = 0.03), von Willebrand factor (p = 0.10), and factor VIII activity (p = 0.10) were positively associated with stroke, whereas HDL-3 was inversely associated (p = 0.02) with stroke." (PMID 17571161, 2007). "In a similar stroke model, ADT-OH reduced tissue plasminogen activator (tPA)-enhanced hemorrhage by inhibiting the protein kinase b/vascular endothelial growth factor/matrix metalloproteinase 9 (Akt/VEGF/MMP9) pathway." (PMID 41465271, 2025). "MMP-9 was significantly higher in patients who presented with a combination of amaurosis fugax, central retinal artery occlusion, TIA and minor/major stroke at follow-up." (PMID 40364266, 2025). "MMP-9 serves as a common denominator in OSA, hypertension, coronary artery disease, and stroke, reflecting its role in inflammation, extracellular matrix remodeling, and vascular dysfunction." (PMID 40117070, 2025).
Stroke (continued). "We found that IL-18, MMP-9, DMTS, DWMH, brain atrophy, previous stroke, hypertension, and female sex were directly and positively correlated with PSCI." (PMID 40821836, 2025). "Studies on stroke and TBI show increased levels of MMP-2 and MMP-9 after injury, with MMP-2 reducing tight-junction integrity and MMP-9 causing complete degradation of the basal lamina and tight junctions." (PMID 40806328, 2025). "Further investigation is needed to clarify the specific role of MMP-9 in OSA, particularly in the subgroups with stroke, coronary artery disease, or COPD." (PMID 40117070, 2025). "Matrix metallopeptidase 9 (MMP‐9), which is elevated in the blood of IS patients within 24 h post‐stroke, contributes to increased BBB permeability and disruption." (PMID 39878387, 2025). "Following the stroke, microglia produce reactive oxygen species, cytokines (e.g. IL-1β), MMP-3, and MMP-9, and they contribute to post-ischemic injury but also in its recovery process." (PMID 38169640, 2024). "Our data reveal ambiguous trends regarding changes in MMP9 and TIMP1 level or MMP9/ TIMP1 during post-stroke rehabilitation and their implications for functional status, as well as their influence on cognition and depression recovery in stroke patients." (PMID 38891934, 2024). "In two studies, almost similar MMP-9 levels were observed in AIS and stroke mimic patients (175 ng/mL ± 149 vs. 175 ng/mL ± 227, p = 0.980; and median 11.6 pg/mL, IQR: 11.2–12.3 vs. 11.8 pg/mL, IQR: 11.3–12.2)." (PMID 39091977, 2024). "Twenty studies in which MMP-9 was measured were included and comprised 2,515 AIS patients and 1,286 controls (HC/matched controls: n = 931, stroke mimics: n = 355)." (PMID 39091977, 2024). "For instance, upregulation of αvβ3 levels post-stroke induces the internalization of important tight junction proteins occludin and zonula occludens (ZO-1) in ECs and promotes the secretion of MMP-2 and MMP-9." (PMID 39000490, 2024). "Moreover, MMP-9 upregulation may induce BBB breakdown post stroke." (PMID 39707430, 2024). "In this study, RIC was associated with increased cerebral blood flow velocity, reduced MMP-9 and increased BDNF suggesting that improved cerebral perfusion, blood–brain barrier integrity and neurogenesis may underlie the effect of long-term RIC in neurological recovery after stroke." (PMID 39702489, 2024). "Therefore, the finding that volunteers who consumed a 1200 mg capsule of black sticky rice and dill extract for one week showed a significant improvement in the severity of NIHSS assessed using the NIHSS and post-stroke disability levels (mRS) could be partly due to a reduction in MMP-9 levels." (PMID 39599732, 2024). "S100B is also included in the Triage® Stroke Panel, which is a rapid fluorescence immunoassay for quantitative measurement of BNP, fibrin degradation products containing D-dimer, MMP-9 and S100B in whole samples blood or plasma." (PMID 39001884, 2024). "In rodent MCAO models, plasma activity of MMP‐9 and MMP‐2 is increased within 3 to 8 hours of stroke onset." (PMID 38379112, 2024). "Neural Progenitor Cell-Derived EVs enhance poststroke BBB integrity via regulating ATP-Binding Cassette Transporter B1 (ABCB1) and matrix metalloproteinase 9 (MMP-9), attenuating inflammatory cell recruitment by inhibition of the NF-κB pathway in stroke mice." (PMID 37728588, 2024). "Indeed, parameters describing the influence of MMP-9 levels in transgenic mouse groups on neural excitability (latency time, spikes number) suggest that the size of the stroke, dependent on MMP-9 activity levels, may have an impact on epileptic parameters in the PTZ-threshold test." (PMID 38255970, 2024). "While previous studies have identified links between MMP-9 and post-stroke depression (PSD), these analyses typically focus on the acute phase of stroke." (PMID 38891934, 2024).
Stroke (continued). "During the early stages of stroke, IL-1 mediates harmful inflammatory processes, such as the upregulation of IL-6, TNF-α, Matrix metallopeptidase 9 (MMP-9), and chemokines in astrocytes, inhibition of neurogenesis." (PMID 36793730, 2023). "In stroke, NBP has potential with its dual role; it has arteriogenic effects and the ability to inhibit the expressions of TNF-α and MMP-9." (PMID 37570794, 2023). "If the HT is considered as delayed (occurs after 18–24h of stroke onset) apart from MMP-2 and MMP-9, MMP-3 as well as endogenous tPA, are involved." (PMID 36835040, 2023). "To investigate the effect of inhibiting IL-10 expression on BBB integrity after PT stroke, we detected changes in MMP2 and MMP9 by RT-qPCR and their activity by gelatin zymography." (PMID 37196130, 2023). "On the other hand, MMP-9 and MMP-2 inhibitors are able to antagonize the BBB damage in the experimental stroke model with fibrin-rich clot used to MCAO." (PMID 36835040, 2023). "After cerebral ischemia, MMP-9 activity is enhanced, resulting in accelerated matrix degradation, BBB disruption, and infarct enlargement during stroke." (PMID 36142283, 2022). "Stroke triggered BBB breakdown and MMP-9 activation, neutrophil infiltration, and increased expression of ICAM-1, which were profoundly attenuated by dBET1." (PMID 35761277, 2022). "Over the recent decades, circulating MMP-9 and BDNF concentrations have been found to have potential value in stroke diagnosis and prognosis." (PMID 36092813, 2022). "Increased evidence found that LCN2 can activate MMP9 by directly binding to MMP9, which finally destroys the integrity of BBB after stroke." (PMID 36187347, 2022). "Overall, the results of the present review are indicative of a link between the circulating levels of BNP, GFAP, RDW, NLR, MMP-9, and AQP4 following stroke and clinical outcome prognostication." (PMID 36278689, 2022). "Although we have investigated the temporal profile of MMP-9 and BDNF concentrations, we emphasize that our results require confirmation in larger sample size and different stroke subtype populations." (PMID 36092813, 2022). "Thus, MMP-9 may be involved in the pathophysiologic process of stroke." (PMID 35370878, 2022). "MMP-9 is known to promote BBB disruption in brain ischemia and ICH, with MMP expression correlating with stroke severity." (PMID 36119117, 2022). "Plasma MMP-9 level has been used as a biomarker for predicting BBB damage and HT in stroke patients." (PMID 35477576, 2022). "Post-ischemic dBET1 treatment significantly reduced MMP-9 levels, neutrophil infiltration into the ischemic brain, and dysregulated levels of cellular adhesion molecules (e.g., ICAM-1) after stroke." (PMID 35761277, 2022). "Meanwhile, stroke-induced BBB disruption, increased MMP-9 levels, neutrophil infiltration, and increased ICAM-1 were significantly attenuated by dBET1 treatment." (PMID 35761277, 2022). "TIMP-3 can inhibit MMP-2, MMP-3, and MMP-9 which regulate ECM structure and vascular remodelling and consequently affect hypertension-induced stroke." (PMID 35444693, 2022). "The CytoHubba plug-in of the Cytoscape was utilized to visualize the genes of stroke-related crucial module, and the top five genes were selected as hub genes using EcCentricity as the ranking method (MPO, MMP9, ITGA2B, ITGB3, and RETN)." (PMID 35557984, 2022). "Following stroke, it has been shown that matrix metalloproteinases (MMPs) play a main role in altering BBB permeability, especially MMP-2 and MMP-9." (PMID 36446955, 2022). "A correlation is found between the higher levels of MMP-9 and increased BBB permeability and the occurrence of severe disease in stroke patients and stroke animal models." (PMID 34976208, 2022). "Matrix metalloproteinase 9 (MMP9), which increased significantly after stroke, is well known as a critical mediator that induces BBB dysfunction and brain edema." (PMID 36187347, 2022).
Stroke (continued). "Following stroke, the levels of MMP-2 and MMP-9 are elevated in ischemic tissue and they contribute to BBB disruption." (PMID 34299322, 2021). "The results strongly suggest that butylphthalide combined with conventional treatment can decrease MMP-9 levels, increase VEGF levels, and reduce the NIHSS scores, possibly improving the prognosis after stroke." (PMID 34987460, 2021). "Here, we aimed to evaluate the effect of Semax in this model via the brain expression profiling of key proteins involved in inflammation and cell death processes (MMP-9, c-Fos, and JNK), as well as neuroprotection and recovery (CREB) in stroke." (PMID 34201112, 2021). "Stroke volume, functional outcome, the BBB integrity, and—in good agreement with the in vitro results—MMP9 secretion as well as EC survival improved significantly in MCC950-treated mice." (PMID 34930895, 2021). "Varying levels within the first 25 h were also described for MMP-9 and TIMP-1 in experimental stroke." (PMID 34899557, 2021). "Upregulated MMP-9 and MMP-2 after stroke degrade TJs, such as occludin and Claudin-5, and microvascular basal lamina." (PMID 34483842, 2021). "VT treatment significantly decreases MMP9 expression and decreases the number of M1 macrophages in the ischemic brain of T1DM‐stroke rats." (PMID 33346402, 2021). "The combination of S100B, B-type neurotrophic growth factor (BNGF), von Willebrand factor (vWF), MMP-9, and monocyte chemotactic protein-1 (MCP-1) provided diagnosis of stroke within 12 h after symptom onset with a 91% sensitivity and a 97% specificity." (PMID 33633673, 2021). "MMP9 plays important roles in inflammation and contributes to increased BBB permeability after stroke." (PMID 33346402, 2021). "The results showed that treatment with BML-111 significantly reduces the size of stroke and protects the cerebral cortex, possibly by reducing BBB permeability, reducing MMP-9 and MMP-3, reducing microglia activation, and protecting tight junctions." (PMID 33921615, 2021). "Only MMP-9 and VEGF were examined, and many other proteins involved in brain damage modulation after stroke are probably also affected by butylphthalide." (PMID 34987460, 2021). "The alleviated systemic inflammation leads to downregulation of ICAM-1, VCAM-1, and MMP-9 in the brain, which preserves the cerebral endothelial glycocalyx and protects the BBB, resulting in protection against stroke injury." (PMID 34612696, 2021). "Previous studies demonstrated that treatment with BMSCs alone significantly increased the expression of angiogenin, MMP9 and ED‐1 in T1DM stroke rats, leading to the failure of BMSCs treatment against stroke." (PMID 34622573, 2021). "Based on the 95 crossover genes identified, PPI network analysis uncovered six core genes including MMP9, MAPK3, PTGS2, JUN, IL1B and TNF likely linking the activity of luteolin to effective stroke control." (PMID 34898370, 2021). "In stroke, MMP-2 and MMP-9 are considered the two most critical enzymes, and therefore, they were among the ones most studied." (PMID 32466129, 2020). "Studies have shown that MMP-9 is not only involved in the pathogenesis of BBB disruption and subsequent vasogenic edema following stroke but also in hemorrhagic transformation." (PMID 33510620, 2020). "As an alternative interpretation, it is also possible that decreased MMP-9 levels/activity following COX-2 blockade is due to reduced activation of microglial cells and astrocytes, which would result in BBB protection after stroke." (PMID 32973660, 2020). "Lastly, we performed IHC analysis of post-mortem brain sections from human stroke patients to determine the cellular location of CD147 as well as levels of both CD147 and MMP-9 in brain tissue." (PMID 32191628, 2020). "In this context, the MMP-9/TIMP-1 ratio was investigated extensively in multiple neurological conditions such as multiple sclerosis, stroke/ischemia, and Alzheimer's disease." (PMID 33384653, 2020).